RUNX1 (RUNX family transcription factor 1)
Diseases named in the same sentence as RUNX1 in open-access papers (continued):
Sharing a sentence is not in itself a finding about the gene and the disease.
myeloid leukemia (continued). "This gene set was heavily enriched with myeloid leukemia drivers (e.g., FLT3, RUNX1, CD33) and other tumor-promoting genes, providing a direct mechanistic link between eccDNA presence and the transcriptional dysregulation that fuels AML." (PMID 41278279, 2025). "Integrative analysis identified 570 genes upregulated at both the eccDNA and mRNA levels, including myeloid leukemia-related genes (e.g., FLT3, RUNX1, and CD33) and oncogenes." (PMID 41278279, 2025). "Among transcriptional factors regulating neuronal differentiation, Runx1, a Runt domain transcription factor also known in mammals as AML1 (acute myeloid leukemia 1), has been demonstrated to play a major role." (PMID 30845786, 2019). "RUNX1 mRNA expression was relatively uniform compared to the RAG genes that displayed markedly higher expression in ALLs compared to normal tissues and myeloid leukemias." (PMID 27056890, 2016). "Third, integrative analysis identified 570 genes upregulated at both the eccDNA and mRNA levels, including myeloid leukemia drivers (FLT3, RUNX1, CD33) and oncogenes (MAP2K2/3, LINC00539), mirroring the “eccDNA–oncogene amplification” axis observed in solid tumors." (PMID 41278279, 2025). "The RUNX1 gene is a Runt-related transcription factor, also known as AML1 (acute myelogenous leukemia 1), that regulates the expression of several important hematopoietic regulator genes, including genes regulating B-cell maturation, granulocyte differentiation, and megakaryocyte maturation." (PMID 33353065, 2020). "Here in this study, we showed that PHF6 played a pro-oncogenic role in myeloid leukemia development induced by RUNX1-ETO9a and MLL-AF9 in mice, while PHF6 is not essential for normal hematopoiesis, suggesting it might be an attractive drug target." (PMID 37393343, 2023). "Indeed, knockdown of RUNX1/RUNX1T1 with small interfering RNA (siRNA) decreased NTAL expression in Kasumi-1 cells, a myeloblast cell line widely used as a model for the study of myeloid leukemias." (PMID 36902005, 2023).
colorectal cancer (49 papers, 2012 to 2026). A primary or metastatic malignant neoplasm that affects the colon or rectum. "Meanwhile, several studies have demonstrated that the abnormally high expression level of RUNX1 in colorectal cancer is closely associated with the occurrence of epithelial-mesenchymal transition (EMT)." (PMID 38430423, 2024). "In summary, the analysis established a significant positive correlation between MUC13 and RUNX1 expression levels, associated with poor prognosis in colorectal cancer." (PMID 39309442, 2024). "All these findings were consistent with the conclusion that MUC13, regulated by RUNX1 transcription in colorectal cancer tissues, was associated with aggressive clinical features and poor prognosis." (PMID 39309442, 2024). "The expression of RUNX1 in tumours is positively associated with immune cell infiltration in various cancers including cervical cancer, colorectal cancer, glioma, and renal cancer." (PMID 36330498, 2022). "Since RUNX1 knockdown reduces cell proliferation in HT29 colorectal cancer cells, the size reduction in the RUNX1-depleted tumors may be caused by lower cell proliferation of the cancer cells." (PMID 34376784, 2021). "Moreover, genetic variations in RUNX1 were associated with colorectal cancer risk." (PMID 27481518, 2016). "In the realm of cancer metastasis and epithelial–mesenchymal transition, the transcription factor RUNX1 (Runt-related transcription factor 1) emerges as a significant player, particularly in colorectal cancer." (PMID 40242037, 2025). "RUNX1's role in promoting colorectal cancer metastasis and regulating TGF-βI-induced epithelial–mesenchymal transition is well-established." (PMID 40242037, 2025). "In some human cancers, the role of RUNX1 is well known; for example, RUNX1 promotes cell proliferation, metastasis, chemotherapy resistance and angiogenesis in colorectal cancer cell lines." (PMID 41020879, 2025). "This integrative approach was designed to offer a comprehensive understanding of the mechanistic influence of RUNX1 on the invasive capabilities of colorectal cancer cells." (PMID 39309442, 2024). "In cohorts of glioma, pancreatic cancer, colorectal cancer, cervical cancer, renal cancer, lung cancer, ovarian cancer, and gastric cancer, RUNX1 is a worse predictive indicator." (PMID 38361095, 2024). "Consistent with these in vitro findings, immunofluorescence results from murine hepatic metastatic tissues further corroborated the notion that RUNX1 induces the EMT phenotype in colorectal cancer cells." (PMID 39309442, 2024). "Collectively, these findings indicated that MUC13 expression levels modulated the metastatic function of RUNX1 in vivo, suggesting that RUNX1 facilitated colorectal cancer cell metastasis partially via MUC13." (PMID 39309442, 2024). "Of particular concern is that, in colorectal cancer, RUNX1 activates the TGF-β signaling pathway, which plays a dominant role in the EMT process of colorectal cancer cells." (PMID 38430423, 2024). "The findings established RUNX1 as a significant promoter of EMT in colorectal cancer, directly implicating it in the enhancement of tumor invasiveness." (PMID 39309442, 2024). "Meanwhile, it has been found that RUNX1 expression is up-regulated in colorectal cancer tissues and this promotes colorectal cancer metastasis by activating the Wnt/β-catenin signaling pathway and EMT." (PMID 38430423, 2024). "Abnormal overexpression of RUNX1 has been observed in ovarian epithelial cancer, renal clear cell carcinoma, gastric cancer, colorectal cancer, and pancreatic cancer." (PMID 38430423, 2024). "Comprehensive in vitro and in vivo studies revealed that RUNX1 substantially enhances cell proliferation, invasion, and migration, thus contributing critically to the progression and metastasis of colorectal cancer." (PMID 39309442, 2024).
colorectal cancer (continued). "In colorectal cancer, RUNX1 is a biomarker for the development of chemotherapy programs and it can activate the Hedgehog signaling pathway by up-regulating the expression of ABCG2, inducing resistance to 5-fluorouracil by colorectal tumor cells." (PMID 38430423, 2024). "The findings suggested that RUNX1 modulated malignant properties in colorectal cancer cells, essentially through the transcriptional regulation of MUC13, which in turn affected EMT." (PMID 39309442, 2024). "In this study, we conducted a comprehensive analysis of RUNX1 expression in colorectal cancer tissues, compared to adjacent normal tissues, using both clinical samples and online databases." (PMID 39309442, 2024). "This interaction correlates with worsened disease outcomes and higher mortality rates, underscoring the potential of the RUNX1/MUC13 pathway as a target for therapeutic intervention in colorectal cancer." (PMID 39309442, 2024). "For example, RUNX1 activation in colorectal cancer correlated with various possible mechanisms, including the Wnt/β-catenin signaling pathway and TGF-β induction through the Smad-dependent pathway and Smad-independent pathway." (PMID 37367670, 2023). "A recent study showed that RUNX1 promotes colorectal cancer metastasis by activating the Wnt/β−catenin signaling pathway and EMT." (PMID 36982956, 2023). "Knockdown of circ_0000512 inhibits cell proliferation and promotes apoptosis in colorectal cancer by regulating miR-296-5p/RUNX1 axis." (PMID 38057816, 2023). "RUNX1 inactivation promotes the occurrence of hematological malignancies and plays a pivotal role in skin, breast, liver, and colorectal cancers." (PMID 36429115, 2022). "In colorectal cancer, overexpression of RUNX1 promotes the ability of cells to migrate both in vivo and in vitro through activating the Wnt signaling pathway." (PMID 36429115, 2022). "What’s more, RUNX1 contributes to activating the Wnt/β-catenin signaling pathway and the epithelial to mesenchymal transition in colorectal cancer." (PMID 36182925, 2022). "Runt-related transcription factor 1 (RUNX1) plays the role of oncogene and anti-oncogene in epithelial tumors, and abnormally elevated RUNX1 is thought to contribute to the carcinogenesis of colorectal cancer (CRC)." (PMID 35836256, 2022). "The RUNX1 gene is frequently reported as overexpressed or amplified in different forms of epithelial cancers such as skin and colorectal cancer." (PMID 36430923, 2022). "Immunohistochemical results showed that most cancer tissues were moderately positive for granular cytoplasm, and RUNX1 was expressed at a medium level in four types of tumors, including cervical cancer, colorectal cancer, glioma, and renal cancer." (PMID 35534796, 2022). "RUNX1 was also shown to be greater in malignancies of the brain and central nervous system, colorectal cancer, and sarcoma." (PMID 35522574, 2022). "To evaluate the effect of RUNX1 in TGFβ1-mediated invasion in colorectal cancer cells, we conducted a wound-healing assay using three different colorectal cancer cell lines including HT29, SW620, or COLO320dm." (PMID 34376784, 2021). "Our data suggested RUNX1 as an upstream transcriptional regulator of ARP2/3 in metastatic colorectal cancer cells in liver metastases." (PMID 34376784, 2021). "C. Expression of RUNX1 mRNA and protein detected by qPCR and western blot in colorectal cancer cell lines." (PMID 31370857, 2019). "B. Overall survival with low/high RUNX1 gene expression was analyzed using a colorectal cancer data set of GSE17536/39582." (PMID 31370857, 2019). "Recent studies have shown the association of RUNX1 and RUNX2 with TGF-beta signalling pathways in colorectal cancer, suggesting a potential association of GATA-1 with CRC through RUNX1SP1." (PMID 22852817, 2012). "RUNX1 expression is increased in several human cancers, such as colorectal cancer." (PMID 41020879, 2025).
colorectal cancer (continued). "RUNX1 mutations, including frameshifts, missense mutations, and gene fusions, are found in a wide variety of tumors such as AML, as well as RUNX1 SNPs in lung adenocarcinoma and colorectal cancer." (PMID 38286983, 2024). "Therefore, up-regulation of this signaling pathway by RUNX1 can promote colorectal cancer cell migration and invasion." (PMID 38430423, 2024). "Furthermore, RUNX1 enhanced the progression and metastatic capabilities of colorectal cancer by upregulating MUC13, which resulted in an increased EMT phenotype and amplified Wnt/β-catenin pathway activity." (PMID 39309442, 2024). "Additionally, RUNX1 enhances liver metastasis of colorectal cancer by activating vessel co-option through ARP2/3." (PMID 38430423, 2024). "Moreover, a significant positive correlation between the expressions of MUC13 and RUNX1 in colorectal cancer tissues provided new insights into RUNX1's role in promoting malignant behavior in colorectal cancer." (PMID 39309442, 2024). "While RUNX1 is well-recognized for its impact on hematological malignancies 7, recent research has illuminated its paradoxical role in solid tumors, including its ambiguous function in colorectal cancer." (PMID 39309442, 2024). "Besides, RUNX1 also plays an important roles in solid tumors metastasis such as colorectal cancer, lung cancer and glioblastoma." (PMID 38172714, 2024). "Conversely, RUNX1 expression induced by TGF-β was high in colorectal cancer tissues (CRC) and its upregulation in vitro and in vivo could expedite CRC cell metastasis by governing the EMT." (PMID 37367670, 2023). "Previous reports have analyzed the role of RUNX1 in colorectal cancer and concluded that RUNX1 may facilitate cancer cell migration." (PMID 37260182, 2023). "On the contrary, RUNX1 activation promoted colorectal cancer cell proliferation." (PMID 36982956, 2023). "Moreover, the transcription factor RUNX1 enhances the Wnt/β-catenin signaling pathway, thereby promoting tumor progression and metastasis in colorectal cancer." (PMID 35534796, 2022). "Study has also shown that RUNX1 could directly interact with β-catenin to enhance the activity of the Wnt signaling pathway in colorectal cancer, thereby enhancing cell migration." (PMID 36429115, 2022). "Based on the expression and prognosis results from the GEPIA database, RUNX1 may act as a potential prognostic biomarker for patients with cervical cancer, colorectal cancer, glioma, and renal cancer." (PMID 35534796, 2022). "In hematopoietic progenitor cells and colorectal cancer cells, RUNX1 transcription is regulated by the Wnt signaling, and LEF1, a co-transcription factor of β-catenin, could interact with RUNX1 and enhance its DNA-binding ability." (PMID 36429115, 2022). "Indeed, TGFβ treatment was found to induce RUNX1 expression in colorectal cancer cells as well as in kidney epithelial cells undergoing EMT." (PMID 34708244, 2022). "To examine our hypothesis, we decided to co-culture (insert co-culturing) IHH hepatocytes with colorectal cancer (HT29 or SW620) cells expressing either control or RUNX1 shRNA." (PMID 36330498, 2022). "RUNX1 has been shown to play significant role during EMT in colorectal cancer cells." (PMID 34708244, 2022). "Importantly, RUNX1 knockdown impaired the metastatic capability of colorectal cancer cells in vivo and induced the development of angiogenic lesions in liver." (PMID 34376784, 2021). "Similarly, we observed that the knockdown of TGFβRII diminishes the function of TGFβ1 towards RUNX1 expression in colorectal cancer cells." (PMID 34376784, 2021). "Genetic variation in RUNX1 has been related to prostate cancer and colorectal cancer." (PMID 31739630, 2019). "Runt-related transcription factor 1 (RUNX1) plays the roles of an oncogene and an anti-oncogene in epithelial tumours, and abnormally elevated RUNX1 has been suggested to contribute to the carcinogenesis of colorectal cancer (CRC)." (PMID 31370857, 2019).
colorectal cancer (continued). "We speculate that the effect of RUNX1 on the prognosis of colorectal cancer as plays a transcriptional regulatory role, plays an important role in the occurrence and development of colorectal cancer depending on the binding of RUNX1 to mitotic regulatory proteins." (PMID 38886545, 2024). "RUNX1 participation in chemotherapy drug response has also been reported in ovarian cancer, glioblastoma multiforme and colorectal cancer, suggesting that this function could be a general molecular mechanism of action that favors tumor aggressiveness against cytostatic drug treatment." (PMID 36766786, 2023). "Runt-related transcription factor 1 (RUNX1) is upregulated in several human cancers, such as colorectal cancer." (PMID 41020879, 2025). "Given our in vitro findings, MUC13 knockdown counteracted the proliferative, migratory, and invasive effects induced by RUNX1 on colorectal cancer cells, prompting a deeper exploration of MUC13's role in RUNX1-driven in vivo tumor progression and metastasis." (PMID 39309442, 2024). "Considering the critical role of EMT in tumor progression, invasion, and metastasis 35, this study investigated the regulatory function of RUNX1 in modulating MUC13 and its subsequent influence on the EMT phenotype in colorectal cancer cells." (PMID 39309442, 2024). "Overall, the results demonstrated that RUNX1 and MUC13 co-modulation distinctly influenced cellular behaviors related to colorectal cancer progression." (PMID 39309442, 2024). "The results demonstrated the pivotal role of the interaction between the transcription factor RUNX1 and MUC13 in modulating colorectal cancer malignancy via the Wnt pathway." (PMID 39309442, 2024). "In colorectal cancer, the activation of the lncRNA RNCR3/AKT signaling axis by RUNX1 promoted tumor invasion." (PMID 38610001, 2024). "Our study of human colorectal cancer tissue microarray (TMA) also revealed positive and statistically significant correlations between the expressions of RUNX1, RUNX2, and RUNX3 in both CD8+T cells and CD103+CD8+T cells." (PMID 39822248, 2024). "These insights significantly contribute to our understanding of the novel interactions between RUNX1 and MUC13 and their substantial impact on Wnt/β-catenin signaling in colorectal cancer." (PMID 39309442, 2024). "TGFβ can induce RUNX1 expression, and RUNX1 knockout can inhibit TGFβ-induced migration and EMT of colorectal cancer cells." (PMID 37760803, 2023). "We successfully knocked down OTX2, RUNX1, MAZ,s and MAFK in HCT116 colorectal cancer cells, respectively." (PMID 35712778, 2022). "Co-culturing hepatocytes with colorectal cancer (HT29, SW620, and COLO320dm) cells resulted in a dramatic increase of RUNX1 protein levels." (PMID 34376784, 2021). "Taken together, these results implied that proper RUNX1 function is necessary for TGFβ1 signaling in EMT and cell invasion in colorectal cancer cells." (PMID 34376784, 2021). "Our results suggested a positive correlation between TSP1 and RUNX1 expression in HT29 and SW620 colorectal cancer cells." (PMID 34376784, 2021). "Knockdown of RUNX1 inhibited proliferation and apoptosis induced by Leucine-rich-alpha-2-glycoprotein 1 (LRG1) in colorectal cancer cells." (PMID 31592165, 2019). "Many targets of miR-675 have been proposed in different tumors, such as Twist1 and RB in hepatocellular carcinoma and colorectal cancer, CALN1 and RUNX1 in gastric cancer, TGFBI in prostate cancer." (PMID 26198047, 2016). "The oncogenic role of RUNX1 in epithelial tumors is increasingly recognized, however, its function and mechanism within the tumor immune microenvironment (TME) of colorectal cancer (CRC) remain unclear." (PMID 41881966, 2026). "From these observations, we inferred that RUNX1 and MUC13 might influence the malignancy of colorectal cancer via the Wnt pathway activity." (PMID 39309442, 2024).
colorectal cancer (continued). "Based on these findings, it was hypothesized that RUNX1 and MUC13 could influence the malignant phenotype of colorectal cancer by modulating the activity of the Wnt pathway." (PMID 39309442, 2024). "Finally, it is worth pointing out that CELF4, TCF7L2, FTO, RUNX1, RUNX3, and CTNNB1 have all been reported to be involved in the etiology of colorectal cancer." (PMID 23626757, 2013). "However, the mechanisms driving colorectal cancer metastasis through MUC13 have not been well elucidated, and the interplay between MUC13 and RUNX1, both critical in CRC and liver metastasis, has not been established." (PMID 39309442, 2024).